GPR87 (G protein-coupled receptor 87)
Diseases named in the same sentence as GPR87 in open-access papers (continued):
Sharing a sentence is not in itself a finding about the gene and the disease.
tumor (24 papers, 2013 to 2025). "GPR87 encodes the G-protein-coupled receptor and plays a crucial role in tumour development and maintenance." (PMID 40987316, 2025). "In conclusion, our findings revealed the regulatory effects and the underlying mechanisms of GPR87 on tumor metastasis in LUAD, implying that GPR87 might be an important prognostic and therapeutic target for LUAD patients." (PMID 35790819, 2022). "First, we assessed the distribution of GPR87 expression in all tumor tissues and found that GPR87 expression was elevated in most cancers." (PMID 35790819, 2022). "Our findings indicate that GPR87 promotes tumor progression and is correlated with immune infiltration, suggesting GPR87 as a possible biomarker for prognosis prediction in LUAD." (PMID 35790819, 2022). "Meanwhile, GPR87 was moderately accurate in predicting tumor and normal outcomes (AUC = 0.758, CI = 0.712–0.804)." (PMID 35790819, 2022). "Based on the analysis of tumour and para-tumour tissues of clinical samples with RNA sequencing, it was found that GPR87 and MAPKs were significantly differentially expressed genes." (PMID 34809653, 2021). "To evaluate the clinical effect of GPR87 silencing on lung metastasis, we used an in vivo tumor model." (PMID 35008182, 2021). "GPR87 overexpression promotes cancer cell proliferation, survival, tumor development, and metastasis." (PMID 35008182, 2021). "Further studies assumed that GPR87 promotes the proliferation of PC stem cells, thus enhancing the malignancy of tumour." (PMID 34809653, 2021). "We compared the expression of GPR87 in normal and tumor lung tissues and found that the expression was significantly upregulated in the tumor tissues in both of the datasets (p = 2.42 × 10−6 for GSE19188 and p = 3.17 × 10−9 for GSE10072, t-test)." (PMID 35008182, 2021). "GPR87 is a cell surface G protein-coupled receptor that is highly expressed in a variety of tumors and plays a crucial role in the survival of tumor cells." (PMID 33029143, 2020). "Among these, RACGAP1, RARRES3, TPX2, MMP28, GPR87, and KIF14 were upregulated and positively associated with poor survival, whereas TSPAN7 was downregulated and identified as a tumor suppressor." (PMID 33033514, 2020). "Over-expression of GPR is associated with tumorigenicity, and several GPRs such as GPR30, GPR87 and GPR110, are implicated in tumor growth and metastasis." (PMID 29422775, 2018). "Immunohistochemical analysis showed that the expression of GPR87 significantly correlated with patients’ clinicopathologic features, including clinical stage and tumor-nodule-metastasis (TNM) classification." (PMID 28288630, 2017). "GPR87 is a G-protein-coupled receptor essential for the development and maintenance of tumours and is a promising novel target for cancer treatment." (PMID 27694942, 2016). "Use of various mRNA expression databases, laser-capture-microdissected (LCM) tissue samples and immunohistochemistry with a panel of human tumors have demonstrated tumor-specific overexpression of GPR87 in many human cancers, including TCC." (PMID 26473854, 2015). "We demonstrated that the overexpression of GPR87 up-regulated CD133 expression, promoted CSC-associated migratory and invasive properties in vitro, and increased tumor initiation in vivo." (PMID 23593389, 2013). "CD133 and GPR87 expression was detected in tumor specimens, the expression of CD133 was correlated with the expression of GPR87 in HCC tissues (R = 0.168, P<0.05)." (PMID 23593389, 2013).
tumor (continued). "Gross examination revealed that 6/6 mice orthotopically inoculated with SMMC-7721-lenti-GPR87 cells developed tumors after 6 weeks, whereas tumor development was only detected in 3/6 mice treated with an equivalent number of SMMC-7721-lenti-control cells." (PMID 23593389, 2013). "Furthermore, our in vivo study demonstrated strong antitumor activity of Ad-shGPR87 against GPR87-overexpressing tumor xenografts for the first time." (PMID 26473854, 2015). "A GPR87-expressing RT112 tumor xenograft model was prepared in scid mice." (PMID 26473854, 2015). "To examine whether the overexpression of GPR87 could also promote tumor growth and metastasis in vivo, we orthotopically inoculated 2×106 SMMC-7721-lenti-GPR87 or SMMC-7721-lenti-control cells into the left hepatic lobe of NOD/SCID mice with a microsyringe." (PMID 23593389, 2013). "In addition, the average tumor size in the mice inoculated with SMMC-7721-lenti-GPR87 cells was 1.6-fold larger than that in mice inoculated with SMMC-7721-lenti-pWPXL cells." (PMID 23593389, 2013). "In addition, there are angiogenesis‐related markers, including ANGPT1, CD40LG, HIF1A, CCL5, and GPR87, which could contribute to tumour vascularisation." (PMID 40754672, 2025). "In addition, PCa patients with high expression of GPR87 had a longer survival time, which indicated that it may act as a tumor suppressor." (PMID 34595101, 2021). "We used the tumor immune dysfunction and exclusion (TIDE) algorithm to assess the effects of GPR87 on the response rates to immune checkpoint (PD-1 and CTLA-4) inhibitors." (PMID 35790819, 2022). "Consistent with the WGCNA results, in the GSE15471 dataset, the TSPOAP1 in the tumor group was significantly lower expressed, while the ADGRG6, GPR87, FAM111B and MMP28 were significantly higher expressed compared with the normal group." (PMID 34809653, 2021). "Consistent with the results of integrated analysis, mRNA expression of RACGAP1, RARRES3, TPX2, MMP28, GPR87, and KIF14 was significantly upregulated in PDAC tumor tissues, whereas TSPAN7 was significantly downregulated." (PMID 33033514, 2020). "Among these DE-MTGs, upregulated RACGAP1, RARRES3, TPX2, MMP28, GPR87, and KIF14 with HR > 1 were regarded as oncogenes, whereas downregulated TSPAN7 with HR < 1 was regarded as a tumor suppressor." (PMID 33033514, 2020). "Conversely, tumors formed by GPR87-silenced PANC-1 cells were smaller and had lower tumor weights than the control tumors." (PMID 28288630, 2017). "To clarify the role of GPR87 in the tumor growth and metastases of CD133+ HCC cells, we first examined the expression of GPR87 in sorted HCC cell lines and primary human HCC cells by qRT-PCR and Western blot." (PMID 23593389, 2013). "G protein-coupled receptor 87 (GPR87), also known as GPR95, is a cell surface GPR that is overexpressed in diverse cancers and plays an essential role in tumor cell survival." (PMID 23593389, 2013). "The overexpression of GPR87 significantly enhanced the migration and invasion of HCC cells, increased their colony formation capacity in vitro and promoted tumor formation and growth in vivo." (PMID 23593389, 2013). "In Cluster 1, we found no genes associated with progressive stages of neoplasia with an FDR < 0.05; however, we observed decreased expression of DSC3 and GPR87 with an FDR < 0.10." (PMID 40844321, 2025). "To extend, GPR87 trans-activated EGFR to promote scattering and extension of tumour cells." (PMID 34809653, 2021). "Apart from overexpression of GPR87, ligands, such as lysophosphatidic acid (LPA), in the tumor microenvironment may stimulate GPR87 and subsequently lead to constitutive activation of cancer-promoting signaling." (PMID 28288630, 2017).
tumor (continued). "Moreover, our recent clinical study of non-muscle-invasive bladder cancer also showed that GPR87-overexpression was correlated with higher tumor proliferation, and that patients with GPR87-positive tumors had a shorter intravesical recurrence-free survival period." (PMID 26473854, 2015).
cancer (23 papers, 2006 to 2025). A tumor composed of atypical neoplastic, often pleomorphic cells that invade other tissues. "Our data indicate that GPR87 overexpression is associated with cancer progression and poor survival outcomes." (PMID 35008182, 2021). "GPR87 encodes a G-protein-coupled receptor and is a viable target molecule for cancer treatment and prevention." (PMID 27694942, 2016). "Next, we examined the relationship between GPR87 and the clinical stages of all TCGA cancers using TISIDB." (PMID 35790819, 2022). "We found that GPR87-overexpressing A549 and A427 cells displayed dramatically increased cancer cell invasion compared to control cells." (PMID 35008182, 2021). "Our results reveal the oncogenic function of GPR87 in cancer progression and metastasis through the activation of eNOS as a key mediator." (PMID 35008182, 2021). "Overexpression of GPR87 promoted cancer cell invasion and a metastatic phenotype, while depletion of GPR87 suppressed these effects." (PMID 35008182, 2021). "EdU test revealed that after knockdown of GPR87, the proportion of cancer cells in S-phase was remarkably reduced." (PMID 32547950, 2020). "Meanwhile, a recent study also showed that Gαi and Gαq contribute to GPR87-mediated NF-κB activation in the 293 T cells, which is ligand-independent, further support the notion that functional NF-κB activation is critical for GPR87-mediated cancer progression." (PMID 28288630, 2017). "In this study, H3F3A affects cancer progression by directly regulating the cancer driver gene GPR87, although in this case, it promotes cancer progression by acting as a transcriptional activator." (PMID 27694942, 2016). "Ad-shGPR87 effectively knocked down GPR87 gene expression in all of the six GPR87-overexpressing cancer cell lines (HT1197, HT1376, J82, RT112, TCCSUP and UMUC3 cells) 3 days after infection." (PMID 26473854, 2015). "Our present results and those of others lend strong support to the possibility that GPR87 plays an important role in cancer cell survival and inhibits apoptosis, and that GPR87 expression is essential for the development and maintenance of cancer cells." (PMID 26473854, 2015). "Moreover, this study lays the groundwork for future experimental work, with in vitro and in vivo validation suggested to evaluate the therapeutic potential and efficacy of these inhibitors as GPR87-targeted cancer therapies." (PMID 40207812, 2025). "GPR87 is upregulated in various tumors and plays an important role in cancer cell survival." (PMID 35008182, 2021). "Elevated GPR87 expression promotes cancer stem cell expansion by regulating the JAK2/STAT3 pathway." (PMID 34290570, 2021). "Finally, GPR87, which belongs to the G protein-couple receptor family, has been shown to be overexpressed in cancers such as pancreatic, non-small-cell lung, bladder and hepatocellular." (PMID 34659201, 2021). "GPR87 takes part in cell communication and is important in cancer pathology." (PMID 33551743, 2020). "Importantly, overexpression of GPR87 upregulates expression of cancer stem cell marker CD133 and promotes the growth and metastasis of CD133+ cancer stem-like cells in hepatocellular carcinoma." (PMID 28288630, 2017). "To determine whether GPR87 influences cancer-related phenotypes, we performed invasion and proliferation assays using GPR87-knockdown cells." (PMID 27694942, 2016).
cancer (continued). "ICC-X1 minimally expresses GPR87, which can promote the growth and metastasis of CD133+ cancer stem-like cells." (PMID 36578029, 2022). "The orphan GPR87 has recently been matched with its ligand LPA, which is a lipid mediator with multiple physiological functions, including cancer cell proliferation." (PMID 23752273, 2013). "Downregulation of GPR87 decreased cancer cell invasion but did not affect cell proliferation in A549 and A427 cells." (PMID 35008182, 2021). "Moreover, we explored the role of GPR87 in regulating the expression of CD133, which in turn promoted the growth and metastasis of cancer stem-like cells in HCC." (PMID 23593389, 2013). "Although the phenotypes were validated only for in vitro models and not for in vivo models, H3F3A and GPR87 both specifically influenced metastasis-related phenotypes but not growth-related phenotypes, suggesting that they mainly influence cancer progression and not tumorigenesis." (PMID 27694942, 2016).
infection (2 papers, 2015 to 2025). The state of being infected such as from the introduction of a foreign agent such as serum, vaccine, antigenic substance or organism. "The expression of CotH3 and GPR87 genes was upregulated after 6 and 16 h of infection with R. oryzae." (PMID 40488471, 2025). "Infection with Ad-shGPR87 effectively downregulated the GPR87 expression, and significantly reduced the percentage of viable cells in 4 of 6 cell lines as detected by an MTT assay." (PMID 26473854, 2015). "The level of GPR87 mRNA was strongly reduced from the first day after Ad-shGPR87 infection." (PMID 26473854, 2015). "As shown by RT112 cells, infection with Ad-shGPR87 at a multiplicity of infection (MOI, PFU/cell) of 10 and 20 effectively knocked down the GPR87 gene expression in a time- and dose-dependent manner (p < 0.005 vs. Ad-scramble, respectively)." (PMID 26473854, 2015).
adenocarcinoma (1 paper, 2021). A common cancer characterized by the presence of malignant glandular cells. "Mice injected with GPR87-silenced cells exhibited significantly suppressed adenocarcinoma cell metastasis in the lung." (PMID 35008182, 2021).
GPR87 also shares sentences with these, for which no sentence is quoted: cervical cancer (2 papers); malignant glioma (1); prostate carcinoma (1).